MAP2K1 (mitogen-activated protein kinase kinase 1)
Diseases named in the same sentence as MAP2K1 in open-access papers (continued):
Sharing a sentence is not in itself a finding about the gene and the disease.
cancer (continued). "Immunohistochemical results showed high expression of MAP2K1 protein in cancer tissues, while adjacent tissues showed low or absent expression." (PMID 39319867, 2025). "MAP2K1 and PIK3CA expression has been observed in various cancers." (PMID 39466748, 2024). "We found that MAP2K1 significantly changed in most cancers, but its expression values are not consistent (CoMI score = 0.20)." (PMID 35439942, 2022). "Conversely, MAP2K1, an essential component of the MAP kinase signal transduction pathway related to cancer hallmark, was not a tissue-specific gene." (PMID 35439942, 2022). "Drugs with targets such as EGFR, ERBB2, MTOR, PARP2, AURKB, MAP2K1 and PLK1 share more similar profiles, which indicates that the inhibition of these targets has specific effects on the in vitro viability and proliferation of cancer cells." (PMID 33795761, 2021). "Identifying MAP2K1 as a potential target of CREB is a step closer to uncovering its regulation, network, and what role it might play in different cancer types." (PMID 30261835, 2018). "MAP2K1 (mitogen-activated protein kinase kinase 1), also called MEK1, is an intra-cellular Cu-dependent kinase involved in the mitogen-activated protein kinase (MAPK) signaling pathway, and thereby is related to cancer growth, invasion, and metastasis." (PMID 28425924, 2017). "It interacts with several large hubs such as MAP2K1, ELAVL1 and PAPOLA1 in the PPI network, and therefore may play important roles in insensitivity of BC cells to cancer drugs." (PMID 28481952, 2017). "Mitogen-activated protein kinase kinase 1 (MAP2K1), a member of the dual-specificity protein kinase family, plays a critical role in transducing intracellular and extracellular signals within the Ras/Raf/MEK/ERK pathway, significantly influencing tumorigenesis and progression in various cancers." (PMID 39319867, 2025). "Moreover, the pathway genes with most links to the query set: MAPK1, MAP2K1, YWHAB, MAP2K2 and MAPK3 are known to be highly expressed in various sorts of cancer, which further highlights the connection to this cancer-derived query set." (PMID 35266519, 2022). "Finally, for DMRs whose associated genes had increased expression upon treatment with FQI1, we observed enrichment of GO terms for pathways in cancer (e.g. PIAS4, SMAD3, TRAF4, MAP2K1) and RNA transport (e.g. NUP188, EIF3A, NUP35, RAN) in both hyper and hypomethylated DMRs." (PMID 27845898, 2016). "The genetic alterations in the three overlapping genes (MAP2K1, PIK3CA and RAF1) revealed by the Damnacanthus indicus C.F.Gaertn prick-related rap1 signal further explored and assessed for the beneficial effects which Damnacanthus indicus C.F.Gaertn may exerts in the treatment of various cancers." (PMID 30906409, 2019). "KIR2DL2/L3/S2+ CD8+ T lymphocytes exhibited over-expression of genes that are not usually expressed in CD8+ T cells, i.e., EGFR, ITGB1, MAP2K1, and CD86, indicating that these cells are reprogrammed to the AKT/PI3K cancer pathway." (PMID 33076479, 2020). "MAP2K1 (also called MEK1) and EGFR were validated as negative regulators by showing that treatment of several cancer cell lines with inhibitors of either enzyme increased mRNA levels and cell surface expression of HLA-A and B2m." (PMID 31112530, 2019).
infection (57 papers, 2007 to 2026). The state of being infected such as from the introduction of a foreign agent such as serum, vaccine, antigenic substance or organism. "In line with previous observations, the expression of kinases belonging to the ERK signaling cascade (MAPK1, MAPK3, MAP2K1, and MAP2K2) remained unaltered after infection, while the levels of some proteins involved in MAPK14/p38 signaling changed significantly." (PMID 36298696, 2022).
adenocarcinoma (8 papers, 2008 to 2025). A common cancer characterized by the presence of malignant glandular cells. "MEK1 (also named MAP2K1) is a serine-threonine kinase with mutations occurring in approximately 1% of NSCLC (mostly adenocarcinoma)." (PMID 26018876, 2015). "Stratification of identified mutations by IHC subgroup revealed a striking enrichment of oncogene mutations in adenocarcinoma-like LC tumors (85% of all oncogene mutations, affecting 63% of these cases), including all nine KRAS mutations and the single NRAS (G12D) and MAP2K1/MEK1 (K57N) mutations." (PMID 26124082, 2015).
neurologic disease (4 papers, 2015 to 2024). "However, few unregulated but intermediate genes in the neurological diseases, cell cycle and cellular development network were correlated to metabolism (Ldl, Erk1/2, Map2k1/2, Creb, Mek) especially through PPAR pathway." (PMID 26439630, 2015). "Recent studies have identified NRAS, KRAS, MAP2K1, and ARAF mutations in RDD patients without documented neurologic disease." (PMID 35236371, 2022).
immune diseases (2 papers, 2022 to 2023). "The component-target-disease network diagram revealed that the essential oil compositions in leaves of C. grandis ‘Tomentosa’ could treat tumors, immune diseases, neurodegenerative diseases and respiratory diseases, which were highly related to CHRM1, PTGS2, CASP3, MAP2K1 and CDC25B." (PMID 35702766, 2023).
metabolic disorders (2 papers, 2015 to 2025). "First, what is the relationship among CDKN1A, FOS, ITGB4, and MAP2K1 in metabolic disorders after MI." (PMID 39069811, 2025).
cardiac disease (1 paper, 2023). "Patients with MAP2K1 variants have a lower frequency of cardiac disease than those with MAP2K2 (64%) and BRAF variants (72%)." (PMID 38136934, 2023).
MAP2K1 also shares sentences with these, for which no sentence is quoted: plexiform neurofibroma (12 papers); multiple myeloma (10); cervical carcinoma (9); acute myeloid leukemia (7); atherosclerosis (7); renal cell carcinoma (7); Cerebral ischemia (6); cholangiocarcinoma (6); endometrial cancer (6); metastatic colorectal cancer (6); osteosarcoma (6); Sepsis (6); triple-negative breast carcinoma (6); uveal melanoma (6); bacterial infection (5); bladder cancer (5); head and neck cancer (5); Hepatic fibrosis (5); LEOPARD syndrome (5); pancreatic ductal adenocarcinoma (5); retinal vein occlusion (5); Alzheimer disease (4); anaplastic thyroid cancer (4); cancer in the skin (4); cardiovascular disease (4); depression (4); diabetes (4); intrahepatic cholangiocarcinoma (4); neuropathy (4); chondrosarcoma (3).
A further 233 diseases each share a sentence with MAP2K1 in 3 papers or fewer.